SIRT1 (sirtuin 1)
Diseases named in the same sentence as SIRT1 in open-access papers (continued):
Sharing a sentence is not in itself a finding about the gene and the disease.
cancer (continued). "Furthermore, SIRT1 has been linked to modulation of cancer epigenetics via regulation of histone acetylation, and may be enhanced by the altered metabolic status of many cancer cells via its dependence upon NAD+ as a coenzyme." (PMID 24258275, 2013). "The initial characterization of AROS as a regulator of SIRT1 found that AROS depletion reduced the viability of the HCT116 cancer cell line." (PMID 24258275, 2013). "The roles of SIRT1 in human cancers are controversial and both SIRT1 inhibitors and activators (such as resveratrol) have been reported to inhibit growth of human cancer cell lines." (PMID 23846322, 2013). "It should be recalled that SIRT1 has been considered an oncogene and a tumor suppressor, depending on the cancer model under consideration." (PMID 24127549, 2013). "SIRT1 antagonization is involved in senescence of mouse fibroblasts, human cancer cells and endothelial cells." (PMID 23989608, 2013). "SIRT1 activation delays some features of aging and protects against liver steatosis, type II diabetes and cancer." (PMID 23841676, 2013). "Previous studies have reported that SIRT1 is overexpressed in several cancer cell lines and cancerous tissue samples." (PMID 22860104, 2012). "Interest has also grown in DBC1 as a negative regulator of SIRT1, particularly in the cancer literature." (PMID 22969813, 2012). "On the other hand, SIRT1 can stimulate oncogenic signaling pathways and can create a tumor microenvironment favorable to growth and survival of cancer cells." (PMID 23050959, 2012). "In ovarian cancer patients, SIRT1 expression predicts a favorable prognosis despite high expression in malignant tumors compared with benign or borderline tumors." (PMID 23024800, 2012). "In this context, the inhibition of SIRT1 is becoming a novel approach for the development of new treatment strategies for some cancers." (PMID 22479397, 2012). "Transient overexpression of SIRT1 was shown to be sufficient to stimulate basal rates of autophagy, which is used by cancer cells to help them survive under stressful tumor microenvironment conditions." (PMID 22479397, 2012). "Silencing SIRT1 activity induces growth arrest and/or apoptosis in human epithelial cancer cells, as well as cisplatin-resistant cancer cells." (PMID 22275802, 2012). "SIRT1 contributes to anti-inflammation, genomic stability, and cancer cell death, and hence it has tumor-suppressor properties." (PMID 23050959, 2012). "Resveratrol is a potent activator of Sirt1 and has multiple effects on metabolism, anti-cancer, anti-ageing and anti-inflammation." (PMID 22069489, 2011). "Consistent with this role of SIRT1, recent evidence indicates that resveratrol inhibits DNA repair in cancer cells." (PMID 22247744, 2011). "Inhibition of Sirt1 was shown to sensitize cells for DNA-damaging cancer therapeutics, and inhibition of Sirt1 and Sirt2 can itself decrease tumor growth." (PMID 21937767, 2011). "Gene expression and deacetylase activity of the class III HDAC SIRT1 are often altered in human cancer tissues." (PMID 21698133, 2011). "Resveratrol can delay cell cycle progression and induce apoptosis in several cancer cell lines; some of these effects have been attributed to the activity of SIRT1." (PMID 22247744, 2011). "Despite the discrepancies with regard to the functional role of SIRT1 in cancer, SIRT1 inhibitors have unanimously shown anti-cancer effects." (PMID 21698133, 2011).
cancer (continued). "This controversy is based on studies of SirT1 expression in cancer and on its wide range of functions, including its activity on well-known oncogenes and tumor suppressors." (PMID 21307403, 2011). "Sirt1 is also involved in epigenetic silencing of DNA-hypermethylated tumor suppressor genes (TSGs) in cancer cells." (PMID 21549004, 2011). "miR-34a regulates SIRT1 expression and inducedsenescence of cancer cells; here, we observed higher miR-34c (notmiR-34a) in senescent cells, likely a reflection of the variability andcomplexity of the senescence process." (PMID 20606251, 2010). "Recently, manipulation of SIRT1 activity has profoundly influenced in vivo models of obesity, neuro-degeneration, diabetes, cancer and aging." (PMID 20975832, 2010). "In this context it is interesting to note that nucleolar JNK2 and SIRT1 proteins are both responsive to metabolic stress and both are also identified as cancer-related survival factors (and this present work)." (PMID 19806201, 2009). "Significantresearch intensity has been placed on understanding the role SIRT1 has incellular transformation and cancer with studies showing both growth-promotingand grow-inhibiting effects of the protein." (PMID 20157516, 2009). "To gain insights into the mechanisms by which SIRT1 reduces cellular proliferation, we examined the effect of SIRT1 on the growth rate of several well characterized cancer cell lines." (PMID 18414679, 2008). "Our findings for a prominent role for SIRT1 in epigenetic silencing of genes whose promoters are hypermethylated in cancer cells has important ramifications for the biology of cancer." (PMID 16596166, 2006). "Here, the authors show SIRT1 is involved in epigenetic silencing of DNA-hypermethylated TSGs in cancer cells." (PMID 16596166, 2006). "The effects of knocking down SIRT1 levels on cancer cell phenotypic features as found in our present study attest to this." (PMID 16596166, 2006). "Strikingly, and correlating with the knockdown pattern of SIRT1 in each cell type, we observed re-expression of key TSGs that are frequently epigentically silenced in a number of different cancers." (PMID 16596166, 2006). "Notably, Sun and coworkers performed a meta-analysis study to investigate the clinicopathological significance of SIRT1 expression in 16 cancer types." (PMID 39858444, 2025). "Several studies utilizing in vitro cell cultures and ex vivo cancer models also demonstrate that SIRT1 inhibitors may be effective treatments for inducing apoptosis and overcoming chemoresistance in cancer." (PMID 40517236, 2025). "Furthermore, SIRT1 promotes DNA damage repair by activating the relevant enzymes through deacetylation, thus impairing the onset of cancer on the one hand while simultaneously promoting cancer cell proliferation at later stages on the other." (PMID 39215785, 2025). "However, in cancer cells, SIRT1 reprograms FOXO1 via site-specific deacetylation of lysine residues (e.g., K242, K245, and K262)." (PMID 41008982, 2025). "However, SIRT1's enzymatic activity can potentially promote cancer progression by inhibiting molecules that lead to apoptosis, contributing to cytotoxicity under certain conditions." (PMID 40708783, 2025).
cancer (continued). "Thus, the interplay between calorie restriction and SIRT1 not only supports cellular longevity and stress resistance but also acts as a metabolic barrier to cancer progression." (PMID 39940361, 2025). "This suggests that SIRT1 may exert tumor-suppressive effects during certain stages of cancer development." (PMID 40567502, 2025). "Additionally, several studies have reported that SIRT1 can promote apoptosis in cancer cells and function as an antitumor factor in cancer progression." (PMID 40989842, 2025). "The authors hypothesized that SIRT1 inhibition in other cells within the cancer microenvironment (i.e., fibroblasts, endothelial, and immune cells) may have been involved in the tumor‐promoting activity of 9a." (PMID 39215785, 2025). "This includes the design of more potent and selective SIRT1 modulators and the evaluation of their efficacy in preclinical models of diseases characterized by ferroptosis, such as kidney diseases, neurodegenerative disorders, and cancer." (PMID 40109363, 2025). "Given that cancer stem cells are responsible for drug resistance and tumor relapse, understanding the mechanism of SIRT1 action in these cells could pave the way for more target-specific therapies." (PMID 40710366, 2025). "Isoforms such as SIRT1, SIRT2, and SIRT6 are mainly associated with tumor-suppressive activities, a function determined by their subcellular localization and the biochemical context of each cancer type." (PMID 41425553, 2025). "Quercetin was also reported to activate SIRT1 (which is also a histone deacetylase appearing to selectively prevent aberrant methylation) in some cancers and its AMPK and mTOR downstream pathways, with histone modification and DNMT regulation likely being involved in these effects." (PMID 39941940, 2025). "SIRT1 exerts anti-cancer effects in CRC by suppressing oncogenes such as β-catenin and survivin." (PMID 40229278, 2025). "SIRT1 can also participate in the process of suppressing cancer by regulating downstream molecules." (PMID 40567502, 2025). "Nonetheless, SIRT1 inhibitors may be useful molecularly targeted cancer therapies with the further elucidation of SIRT1’s function." (PMID 40517236, 2025). "Collectively, these results suggest that SIRT1 acts as a molecular switch that determines whether FOXO4-mediated senescence is sustained or bypassed in cancer cells." (PMID 41008982, 2025). "Additionally, some anti-cancer agents, such as Manuka honey and Xanthohumol, exert their effects by inhibiting the SIRT1/PGC1-α axis." (PMID 40567502, 2025). "Importantly, overexpression of SIRT1 effectively reduced the migration and invasion of cancer cells and decreased angiogenesis, suggesting its therapeutic potential in the treatment of this aggressive disease." (PMID 40664665, 2025). "Additionally, SIRT1 activators such as resveratrol have shown anti-tumor potential in preclinical cancer models." (PMID 41213956, 2025). "SIRT1 may play multiple—and potentially opposing—roles in cancer, either contributing to tumorigenesis or protecting cells from it." (PMID 40507674, 2025). "In various cancer types, SIRT1 has significant functional diversity." (PMID 40754534, 2025). "The regulation of SIRT1 based on NAD+/NADH ratio is also seen in other molecules, Ubiquitin specific protease 22 (USP22) is a deubiquitinase that is believed to be associated with various cancers." (PMID 40567502, 2025). "SIRT1 has been proven to play a criticalrole in modulating a wide range of physiological processes, includingapoptosis, DNA repair, inflammatory response, metabolism, cancer,and stress." (PMID 40657099, 2025).
cancer (continued). "This review highlights what scientists currently know about SIRT1 in these cancers and suggests that, with further research, targeting SIRT1 could help improve outcomes for patients, especially those with hard-to-treat tumors." (PMID 41300302, 2025). "Below, we discuss the key SIRT1 inhibitors that have shown potential for cancer therapy." (PMID 41008982, 2025). "Understanding how and when to block SIRT1 could lead to more effective, personalized cancer therapies in the future." (PMID 41300302, 2025). "This cascade of events underscores metformin’s capacity to harness the SIRT1/NF-κB signaling axis to drive pyroptosis and positions metformin as a novel therapeutic option to induce pyroptotic cell death in cancer cells, particularly those resistant to traditional apoptotic pathways." (PMID 40149884, 2025). "This duality underscores the complexity of SIRT1’s function and suggests that its role may vary depending on the stage of cancer and the specific molecular context." (PMID 40567502, 2025). "MiRNA-34a can also downregulate the expression of SIRT1, exerting anti-cancer effects." (PMID 40567502, 2025). "While SIRT1 acts as a key player in both Type I and Type II EC, its regulation and functional effects differ between the two subtypes, influencing tumorigenesis and cancer progression." (PMID 41300302, 2025). "Whether it is through the suppression of tumor growth and metastasis, or by playing a pivotal role in overcoming chemotherapy resistance, SIRT1 clearly demonstrates its anti-cancer potential in GC." (PMID 40567502, 2025). "In addition to the occurrence of cancer, SIRT1/Wnt/β-catenin signaling pathway is also involved in many other stages of CRC." (PMID 40567502, 2025). "Moreover, elevated NAD+ levels under stress conditions further amplify SIRT1 activity and substrate deacetylation, collectively enabling cancer cells to adapt to oxidative, inflammatory, and metabolic stress." (PMID 41008982, 2025). "SIRT1 inhibitors are gaining attention as innovative approaches to cancer therapy." (PMID 41008982, 2025). "Intriguingly, SIRT1 appears to have a dichotomous role in cancer as an inhibitor and/or promoter." (PMID 39858444, 2025). "Concerning the experiments in cancer cells, the correlation between SIRT1 inhibition and the reported effects should be interpreted cautiously, since the doses employed (e.g., 50 μM or even more) in some studies may have also determined SIRT2 inhibition." (PMID 39215785, 2025). "SIRT3 exhibits context-dependent roles in cancer, similar to SIRT1 and SIRT2." (PMID 41304967, 2025). "Moreover, upon attack by anti-cancer therapies, SIRT1 deacetylates β-catenin, promoting its translocation from the nucleus to the cytoplasm." (PMID 40567502, 2025). "However, MHY2245, a new SIRT1 inhibitor, by inhibiting the activity and expression of SIRT1, leads to cell cycle arrest, apoptosis, and autophagy in cancer cells." (PMID 40664665, 2025). "SIRT1 controls inflammation, cell cycle abnormalities, and aberrant metabolic control in cancer." (PMID 41233892, 2025). "Thus, SIRT1 serves as a critical mediator of the anti-tumor effects of calorie restriction, integrating metabolic adaptations with cancer prevention by regulating lipid metabolism, inflammation, and cellular stress responses." (PMID 39940361, 2025). "Furthermore, SIRT1 expression and activity tend to decline with age, contributing to age-related diseases such as cancer, neurodegeneration, and cardiovascular disorders." (PMID 40710366, 2025). "One protein that may play a key role in these cancers is Sirtuin 1 (SIRT1), which helps control important cell functions like DNA repair, cell survival, and stress response." (PMID 41300302, 2025).
cancer (continued). "SIRT1 deacetylates autophagy-related proteins, such as beclin 1 and microtubule-associated protein 1 light chain 3 (LC3), facilitating the autophagic survival of cancer cells under metabolic stress." (PMID 40052151, 2025). "Alpha-cyano-4-hydroxycinnamate, a lactate transporter inhibitor, may also promote SIRT1 overexpression and decreased N-cadherin expression of cancer cells, leading to reduced tumor cell migration and reduced cancer cell aggressiveness in RCC." (PMID 40227577, 2025). "We synthesized mechanistic insights into SIRT1 interactions with its substrates, highlighted cancer type-specific functions in ovarian, breast, liver, lung, and gastrointestinal malignancies, and critically evaluated the dual role of SIRT1 as both a longevity factor and an oncogenic driver." (PMID 41008982, 2025). "SIRT1 activators have demonstrated therapeutic potential in mitigating fibrosis, reducing oxidative stress, and preventing liver injury, while SIRT1 inhibitors show promise in cancer therapy by inducing apoptosis in HCC." (PMID 40052151, 2025). "Whole-body SIRT1 moderate overexpression improved healthy aging and protected mice from metabolic-syndrome-associated cancer, preventing metabolic damage induced by a high-fat diet; however, this SIRT1 overexpression failed to extend longevity." (PMID 38784035, 2024). "In addition to promoting apoptosis, SIRT1 activation also stimulates autophagy, a process that allows cancer cells to degrade damaged organelles and proteins, thus reducing oxidative stress and promoting cell survival under stress conditions." (PMID 39403142, 2024). "Furthermore, miR-34a downregulates Notch, Jag1, and SIRT1, impairing cancer stem cell self-renewal and reducing cancer cell invasiveness 70-75." (PMID 39512697, 2024). "SIRT1 regulators have emerged as autophagy modulators in cancer." (PMID 39403142, 2024). "In addition to SIRT1, other hub genes like EGFR have been implicated in autophagy-related pathways, particularly in cancer biology, where EGFR’s role in autophagy regulation is well established." (PMID 39494277, 2024). "The study suggests that focusing on understanding of the regulatory effect of ISG15 conjugation to SIRT1 could enhance cancer treatments." (PMID 38443596, 2024). "We suggest that differences in SIRT1 mutations and polymorphisms may be one of the causes for differences in predicting OS and TNM stage and lymphatic metastasis of cancer on the basis of SIRT1 expression." (PMID 39403142, 2024). "Indirect evidence also suggests that SRT1720, SRT2183, and SRT1460, as activators of SIRT1, may modulate autophagy to initiate cancer cell death pathways." (PMID 39403142, 2024). "Therefore, our findings pave the way for understanding the regulatory mechanism of SIRT1 in cancer cell fate decisions." (PMID 38443596, 2024). "SIRT1 deletion in senescent stromal cells supports accelerated production of inflammatory exosomes, significantly alters the expression profile of recipient cancer cells, enhances their aggressiveness, and promotes cancer resistance." (PMID 39596439, 2024). "Our study used KM analysis to evaluate the prognostic value of SIRT1 in 33 types of cancer." (PMID 39845948, 2024). "This activation of SIRT1 by resveratrol could be particularly useful in treating drug-resistant cancer cells and eliminating cancer stem cells." (PMID 39403142, 2024). "Therefore, investigating the mechanisms of SIRT1 in pan-cancer is crucial for advancing cancer treatments." (PMID 39845948, 2024). "SIRT1 interacts with mTOR to regulate autophagy in human cancers." (PMID 39403142, 2024).